ZNF765 (zinc finger protein 765)
Description:
May be involved in transcriptional regulation.
Tractability: PROTAC: UniProt records ubiquitination sites on it; ubiquitination databases record sites on it.
Gene: Protein-coding gene on chromosome 19 (53,389,793 to 53,430,413, forward strand). Ensembl gene ENSG00000196417.
Subcellular location: Nucleus
Pathways (Reactome):
Gene expression (Transcription): Regulation of endogenous retroelements by KRAB-ZFP proteins
Gene Ontology:
Molecular function: protein binding; DNA-binding transcription factor activity, RNA polymerase II-specific; RNA polymerase II cis-regulatory region sequence-specific DNA binding
Biological process: regulation of transcription by RNA polymerase II; regulation of DNA-templated transcription
Cellular component: nucleus
Genetic constraint (gnomAD): Loss-of-function variants: 37 observed, 45.31 expected, observed/expected ratio (o/e) 0.82, 90% interval 0.63 to 1.07. The upper end of that interval is the gene's LOEUF score, 1.07, which puts it in group 4 of 6, group 1 being the genes least tolerant of losing a copy. Missense variants: 594 observed, 640.39 expected, observed/expected ratio (o/e) 0.93, 90% interval 0.87 to 0.99. Synonymous variants: 201 observed, 215.84 expected, observed/expected ratio (o/e) 0.93, 90% interval 0.83 to 1.05.
Homologues: Orthologues: chimpanzee ZNF765 (89% identical). Paralogues in human: ZNF761 (80% identical), ZNF813 (79% identical), ZNF578 (72% identical), ZNF888 (70% identical), ZNF860 (69% identical), ZNF525 (69% identical), ZNF468 (66% identical), ZNF816 (65% identical), ZNF701 (63% identical), ZNF766 (46% identical).
Diseases named in the same sentence as ZNF765 in open-access papers:
ZNF765 is named in the same sentence as 6 diseases in open-access papers, as found by Europe PMC text mining. Sharing a sentence is not in itself a finding about the gene and the disease. The quoted sentences say what the papers report.
hepatocellular carcinoma (1 paper, 2023). A malignant tumor that arises from hepatocytes. "We have attested that ZNF765 expression was associated with immune infiltration in hepatocellular carcinoma and with poor prognosis in patients." (PMID 37400985, 2023). "In a nutshell, our study illustrates the fact that ZNF765 may be a potential biomarker that promotes the progression of hepatocellular carcinoma and is associated with a poor prognosis." (PMID 37400985, 2023). "The association of ZNF765 with T cell checkpoints was evaluated to facilitate the guidance of immunotherapy in patients, as immune checkpoint therapy has been reported to bring benefits to patients with hepatocellular carcinoma." (PMID 37400985, 2023). "This study evaluated the expression of ZNF765 in hepatocellular carcinoma and the impact of its expression on patient prognosis based on The Cancer Genome Atlas (TCGA)." (PMID 37400985, 2023). "Further, half maximal inhibitory concentration confirmed the effect of ZNF765 expression on the sensitivity of hepatocellular carcinoma cells to effective docetaxel and bleomycin used in the treatment of patients with hepatocellular carcinoma." (PMID 37400985, 2023). "The objective of our study was to assess the expression, prognostic value, and biological effect of ZNF765 in hepatocellular carcinoma by using a variety of bioinformatics analysis methods." (PMID 37400985, 2023). "In conclusion, ZNF765 may be a prognostic biomarker related to cell cycle, immune infiltration, m6A modification, and drug sensitivity for hepatocellular carcinoma." (PMID 37400985, 2023). "We found that T cell checkpoints CTLA-4, PD-1, and PD-L1 were closely related to ZNF765, and the number of multiple subtypes of T cells may have an effect on the prognosis of patients with hepatocellular carcinoma." (PMID 37400985, 2023). "To sum up, we believe that ZNF765 may participate in immune infiltration and immune escape in hepatocellular carcinoma patients." (PMID 37400985, 2023). "In our research, ZNF765 may not only affect the cell cycle but also act on the microenvironment of hepatocellular carcinoma to regulate tumor-infiltrating immunity and m6A modification and influence patient sensitivity to drugs." (PMID 37400985, 2023). "The COX model showed that ZNF765 could be an independent prognostic factor for hepatocellular carcinoma, which highlighted the prognostic role of ZNF765 in hepatocellular carcinoma." (PMID 37400985, 2023). "Moreover, immunohistochemistry and a colony formation assay confirmed the overexpression of ZNF765 in hepatocellular carcinoma and its promoting effect on the proliferation of this cancer." (PMID 37400985, 2023). "Consequently, we hypothesized that ZNF765 may promote hepatocellular carcinoma through the m6A regulatory factor." (PMID 37400985, 2023).
lymph node metastasis (1 paper, 2023). "However, the expression of ZNF765 was not correlated with N (lymph node metastasis)." (PMID 37400985, 2023).
metastatic cancer (1 paper, 2023). A carcinoma which has spread from the original site of growth to another anatomic site. "As a result, ZNF765 was found to be significantly more abundant in metastatic cancer than in primary cancer." (PMID 37400985, 2023).
metastatic tumor (1 paper, 2023). "Moreover, we used the HCMDB online website to draw the expression box plots of ZNF765 in primary tumor and lung metastatic tumor tissues." (PMID 37400985, 2023).
tumor (3 papers, 2022 to 2024). "Zinc finger protein 765 is a zinc finger protein related to the permeability of the blood–tumor barrier." (PMID 38891944, 2024). "The effect of ZNF765 expression on tumor immune infiltration is also in the process of being analyzed." (PMID 37400985, 2023). "Chemokines are small proteins involved in immune cell migration, tumor growth, and immune regulatory dynamics, which is why we suspect that they are the key factors mediating ZNF765’s effect on immune cell infiltration." (PMID 37400985, 2023). "The DNA methylation level of ZNF765 in tumor samples from LIHC was slightly lower than that of normal samples (p < 0.001)." (PMID 37400985, 2023). "Then, the Wilcoxon rank sum test was used to generate differential expression maps and paired differential expression maps to examine the specific circumstances of ZNF765 expression between normal and tumor samples." (PMID 37400985, 2023). "Zinc finger protein 765 (ZNF765) is an important zinc finger protein that is related to the permeability of the blood-tumor barrier." (PMID 37400985, 2023). "In a word, ZNF765 had a positive relation with the purity of the tumor, and the expression ZNF765 was obviously related to the level of HCC immune infiltration and evasion." (PMID 37400985, 2023). "We further compared the abundance distribution in tumor-infiltrating immune cells with different ZNF765 somatic copy number alteration (SCNA) via TIMER." (PMID 37400985, 2023). "One article correlated with cancer mentioned that ZNF765 was closely related to the regulation of the blood-tumor barrier." (PMID 37400985, 2023). "Consequently, FBXL19-AS1 may modulate the blood-tumor barrier permeability by negatively controlling ZNF765 via STAU1-induced mRNA decay." (PMID 36649030, 2022).
cancer (1 paper, 2023). A tumor composed of atypical neoplastic, often pleomorphic cells that invade other tissues. "It proclaimed that, in comparison with normal tissues, ZNF765 had an increased expression in a wide range of cancer tissues." (PMID 37400985, 2023).